CD44 (CD44 molecule (IN blood group))
Diseases named in the same sentence as CD44 in open-access papers (continued):
Sharing a sentence is not in itself a finding about the gene and the disease.
tumor (continued). "In this study, we hypothesized that CD44-ve cells exist in tumors in addition to conventional CSCs and that these cells, which emerge when the chemotherapeutic agents’ concentration and overall tumor stress increase, are involved in tumor growth and resistance after chemotherapeutic agents." (PMID 37523119, 2023). "In this study, we attempted to match tumor outcomes with the expression of the following stem cell markers: ALDH1, AnnexinA1, CD44, CD117, CD166, Nanog and oct-4." (PMID 38188613, 2023). "The results showed that CD44 and CD133 were highly expressed in ESCC tissues and the expression level was also correlated with tumor staging." (PMID 37607071, 2023). "For example, in the case of GIST, CD44 and CD133 are constant in CSCs of this type of tumor, both in isolation using induction media and in biopsy studies." (PMID 37173919, 2023). "These analyses also showed that expression of VIM, TGFβ1, α-SMA, CD44 and CD133 had significantly high expression in metastatic compared to primary tumours." (PMID 37174052, 2023). "It has also been reported that CD44+ cancer cells contain CSC-like properties and can initiate in vivo tumor formation." (PMID 37108495, 2023). "TRRAP knockdown decreased the expression of CD44, a CSC marker that regulates self-renewal, tumor initiation, and cancer metastasis." (PMID 37047234, 2023). "Recent studies have shown that CD44 is the most common CSC surface marker and plays an essential role in communication between CSCs and the tumor microenvironment." (PMID 36831554, 2023). "The expressions of CD44 and CD69 and those of granzyme B (GrB) and IFN-γ, which is involved in tumor eradication, were analyzed by flow cytometry." (PMID 37875555, 2023). "For instance, markers of both leukocyte activation (CD44) and exhaustion (LAG3) were also highest in the Brca1-null tumours." (PMID 38017453, 2023). "Hypoxia promotes a stem-like phenotype in tumor cells through the activation of genes such as OCT4, SOX2, c-MYC, CD44, CD133, WNT, Notch, and NANOG, leading to dedifferentiated and undifferentiated tumor phenotypes associated with more aggressive biology." (PMID 38132455, 2023). "CD44 is a transmembrane protein found in various CSCS; it performs a critical function in controlling the self-renewal, tumor initiation, treatment resistance, and metastatic features of CSCs." (PMID 36675306, 2023). "Although an anti-pan-CD44 mAb, C44Mab-46 recognized not only OSCC tissues, but also stromal tissues, C44Mab-108 stained the tumor tissues selectively." (PMID 36975491, 2023). "Our results confirmed the spatial proximity of multiple sets of ligands and receptors, such as ANXA1‐FPR1, APP‐CD74, MIF‐(CD74 + CD44), and CD99‐CD99, and they basically correspond to the location of tumor cells, myeloid cells, and T cells, respectively." (PMID 37021816, 2023). "qPCR analysis showed that the expression of CD133, CD44, and OCT4 and SOX2, EpCAM, and LGR5 in CSC sphere cells enriched after the addition of micro serum was higher than that in tumor cell spheres enriched in serum-free medium." (PMID 37639070, 2023). "In the analysis of L/R pairs, the L/R pairs of MIF/(CD74 + CD44 or + CXCR4) and APP/CD74 were the most prominent interactions involving signal transduction from tumor cells to PCs." (PMID 37138324, 2023). "From a CRC viewpoint, the epigenetic landscape of the xenografted tumours (e.g., originating from SK-N-SH CD44+ and CD44− cells) showed a noradrenergic phenotype (group I), suggesting that in vivo cues induced transition to adrenergic status." (PMID 37887559, 2023). "In contrast, we found that inflammatory interactions between tumor cells or Scissor+ tumor cells and myeloid cells were significant increased, such as APP‐CD74, and MIF‐(CD74 + CD44)." (PMID 37021816, 2023).
tumor (continued). "Cancer stemness markers have been reported in cell populations with elevated CD44 and reduced CD24 expression levels that exhibited the same drug-resistant histopathological features of the derived tumor when injected in mice at very low concentrations." (PMID 37169743, 2023). "Both CD44 and CD133 are also included in the panel of markers reported to characterize the tumor-initiating cell (TIC) phenotype in PDAC." (PMID 36831395, 2023). "Overexpression of cortactin could contribute to the emergence of invasive tumor phenotypes in a variety of ways, including enhanced actin polymerization, down-regulated epidermal growth factor receptor, and molecule interactions between cyclin D1 and CD44 proteins." (PMID 38077360, 2023). "Among all patients with CODEX data, a positive correlation between the expression of CD45 and CD44, CD4 and CD45 inside tumor was observed (R > 0.9, p < 0.0001)." (PMID 38223688, 2023). "It has been demonstrated that CD44 regulates expression and activation of integrins VLA-4 and LFA-1 on the surface of leukocytes and tumor cells." (PMID 37174657, 2023). "Intriguingly, in the more invasive tumor regions, there was a notable shift in the staining profile: invasive tumor cells exhibited strong ALDH1 positivity and decreased CD44 positivity." (PMID 38126564, 2023). "This suggests that CD44 is involved in the expansion of CSC populations in cancers, allowing for tumor growth and recurrence." (PMID 37958796, 2023). "Breast CSCs are distinguished by their CD44+/CD24- phenotype and can generate circulating tumor cells, thereby facilitating tumor invasion and metastasis." (PMID 38273859, 2023). "Similar to the results from primary resistant cells, GAA treatment was also effective in reducing the percentage of CD133+CD44+ cells, mRNA levels of the CSC-specific transcription factors, and the number of tumor spheroids for these acquired-resistant cells." (PMID 37452037, 2023). "Interestingly, GBM organoids cultured in engineered hydrogels with low HA content were approximately three times more sensitive to anti‐tumor drugs than that in stiffness‐matched matrices with high HA content, and knockout of CD44 could counteract this resistant phenotype." (PMID 37081739, 2023). "Functionally, the TRIB3high tumor epithelial cell was highly enriched in ribosomes and PCD-related pathways, representing its high metabolic demand, while its high expression of CD44 suggests a high degree of stemness." (PMID 37153569, 2023). "CD44-ICD, after entering the cell nucleus, promotes tumor cell proliferation, migration, angiogenesis, and metastasis." (PMID 37064130, 2023). "By comparing 2D and 3D cell culture techniques regarding the expression of ANXA1, CD44, KRT18, OCT4, and SOX2OT genes, folding results represented variation in gene expression between tumor cells cultivated in 2D and 3D cultures." (PMID 37884554, 2023). "tumor and/or ascitic fluid of 16 patients were characterized for MSCs phenotype (CD73, CD90, CD105), CSCs markers (CD24, CD44, CD133), and hematopoietic stem and progenitor marker (CD34) and leukocyte common antigen (CD45)." (PMID 37958844, 2023). "circCABIN1 KD substantially suppressed tumorigenicity upon in vivo serial passaging of sorted CD44+CD133+ cells, suggesting that circCABIN1 KD impaired the tumor formation ability of GSCs." (PMID 36755314, 2023). "Mice treated with the combination of ICIs and FMD showed only a trend for increased accumulation of cytotoxic NK cells (CD45+Nkp46+GzmB+) inside the tumor and increased expression of CD127 by CD8+CD44+ effector T cell compared to ICI alone." (PMID 37684243, 2023). "In our study, we detected 17 immune-related markers inside the tumor of HCC patients, then we found CD44, CD20, CD68, HLA-DR, and CD31 as the prognosis-related markers using LASSO Cox regression model." (PMID 38223688, 2023).
tumor (continued). "Concurrently, an elevated protein expression of CD44 was detected in ccRCC tumor tissues within the CPTAC cohort, with a significant correlation between CD44 levels and the tumor stage of ccRCC patients." (PMID 37509716, 2023). "Studies have shown that the interaction between CD44 and HA contributes to GBM pathogenesis by promoting tumor cell survival, proliferation, and invasion." (PMID 37366874, 2023). "The CD44 protein expression in HNSCC and normal tissues was ascertained using the National Cancer Institute's Clinical Proteomic Tumor Analysis Consortium Head-and-Neck cancer dataset (108 primary HNSCC and 71 normal tissues)." (PMID 37593530, 2023). "In the tumor compartment, patients with PR had higher expression of ER-alpha, PD-L1, Pan-AKT, CD68, Ki-67, and Fibronectin, but lower expression of CD44, CD127, CD34, and VISTA." (PMID 37153589, 2023). "Together, these results indicated that the LeptoM3 and BCB adhesion cells expressed higher stemness markers CD44, CD133, and EPCAM and lower CD24 and the overexpression of ICAM2 promoted sphere formation and tumor initiation." (PMID 37620448, 2023). "Severe hypoxia (0.5–2.5% O2) upregulates hypoxia-inducible factor (HIF)-1α, which then activates target genes, including CD44, TGF-β, and cMET, all of which are related to tumor migration and invasion." (PMID 37835592, 2023). "IGF2BP3 is an RBP and can affect tumor progression by targeting mRNA for MMP1, CD44, CDK164, ABCG2, IGF2 and other genes." (PMID 37340423, 2023). "CD44 has been investigated as a cancer stem cell marker of HNSCC and plays a critical role in tumor malignant progression." (PMID 37504249, 2023). "Cells harboring CD44, a CSC marker, were magnetically separated from the heterogeneous tumor cell populations." (PMID 36902135, 2023). "CD44 knockdown in MDA-MB-231-BR significantly reduced the pericellular HA-coat on these cells, and, consequently, tumor cell adhesion and invasion through the brain endothelium." (PMID 36291142, 2022). "In the present study, NK cell markers were detected in human GBM tissue sections in close proximity of tumor vasculature and cells positive for GSLC markers SOX2 and CD44." (PMID 35538218, 2022). "More than just being a marker, CD44 also plays functional roles in CSC properties, many of which are also recognized EMT-driven properties, including self-renewal, plasticity, tumor initiation, metastasis, and chemo/radio resistance." (PMID 35805061, 2022). "Bulk-RNAseq and scRNAseq revealed that, in addition to NAMPT inhibition, FK866 regulates tumor metastasis, cell migration, invasion, DNA repair machinery, redox homeostasis, autophagy, as well as cancer stemness–related genes, HES1 and CD44." (PMID 36497496, 2022). "In this study, both in vitro and in vivo experiments revealed that metformin inhibited OC cell proliferation, the proportion of CD44+/CD117+ CSCs, tumor growth, and HIF-1α expression." (PMID 36046821, 2022). "It is also noteworthy that A549stc1ko tumor cells not only expressed lower levels of CSC markers, but also appeared to have more CD44-low and CD166-low cells." (PMID 36499099, 2022). "Here we show that the mammosphere-promoting functions of exosomal CD44 and CD81 illustrate the crosstalk between tumor-initiating cells and surrounding cancer cells that potentially contributes to their self-renewal and/or plasticity." (PMID 36193887, 2022). "Ongoing in vitro experiments in our laboratory, aim to identify and validate the molecular players that link the activation of CD44, by its ligand HA, to the transcriptional regulation of PCF11 3’UTR to promote tumor cell invasion and metastasis." (PMID 35756640, 2022).
tumor (continued). "Intriguingly, we found that both CD44 and CD206 were mainly expressed at the tumor invasive front, with significantly weak expression in the tumor inner." (PMID 35680853, 2022). "We also found a visibly stronger expression of L1-CAM, CD44, and ITGB4 in the scid mice primary tumours and lung metastases injected with Fra-2 overexpressing cells by immunohistochemical staining." (PMID 34693476, 2022). "The SHH signaling pathway is involved in normal embryogenesis development and plays a key role in the promotion of tumor growth and in drug resistance, upregulating the genes involved in CSC maintenance, such as CD44, CCND2, c-MYC, NANOG, OCT4, and ALDH1." (PMID 36498571, 2022). "In this study, the HA-mPEG-Cis NPs were synthesized by self-assembly, which can target CD44-positive CRC cells and dissolve the PEG hydration layer responsive to the weakly acidic tumor environment." (PMID 36033392, 2022). "Multiple studies have investigated the role of CD44 in GBM cells and have highlighted a link between tumor malignancy and CD44 expression." (PMID 35992852, 2022). "Based on this intriguing discovery, we subjected equine HNSCC section to immunofluorescent CD44/CD271 double staining, revealing the intralesional presence of CD44+CD271+ tumor cells in all tumors analyzed." (PMID 35215208, 2022). "According to previous reports, the functions of CD44, ADM, TYMS, and MKI67 are primarily in promoting the Warburg effect and tumor growth in various cancers, while the function of those four genes in DTC has rarely been reported." (PMID 35528004, 2022). "In general, the CD44-/CD105- subpopulation showed different metabolic profiles and a particular tumor evolution pattern, resulting in accelerated growth in only seven weeks compared to the other tumors, thus depicting greater aggressiveness." (PMID 36612281, 2022). "We identified significantly increased mRNA levels of the CCNB1/CDC42/MAPK7/CD44 oncogenes in pan cancers, including GBM tumor tissues compared to normal tissues from TCGA, using the TIMER bioinformatics tool." (PMID 35008426, 2022). "In fact, there are a few reports suggesting that most of these treatments enhance the fraction of CD44+CD24− cells and ALDH+ cells, i.e., BCSCs within the tumour cells." (PMID 35159385, 2022). "The relationship of CD166 vs CD133 vs CD44 with age revealed a similar higher expression of CD166 and CD133 in the normal tissue of patients under 65 and in the tumor tissue of the patients over 65 years old." (PMID 36291969, 2022). "Myeloid and tumour cell-expressed OPN and CD44 act as an immune checkpoint to suppress T cell activation and confer host tumour immune tolerance." (PMID 36316684, 2022). "Fresh-frozen tissue sections were fixed with PFA and stained with IF probes targeting CD44 and ALDH1 to determine the stem cell-like microniche within the tumour." (PMID 35534484, 2022). "In the present study, we found that AGK enhanced the tumor sphere potential and the expression of stemness genes increased, such as ALDH1, SOX2, OCT4, NANOG, LIN28 and EOC stemness gene CD44." (PMID 35934718, 2022). "The CD receptor family comprises surface receptors mainly present on cancer stem cells (CSCs), including CD14, CD22, CD36, CD44, and CD133, which can be used as promising delivery targets against tumor metastasis." (PMID 36096856, 2022). "Markers CD24, CD44, PDX1, synaptophysin, CD49, CDX2, CD45, DAXX, PCAD and CK7 had lower expression in the tumour relative to that in the non-tumour with the exception of one patient." (PMID 36362433, 2022). "Next, we addressed to count directly in vivo the percentages of naïve (CD44−CD62L+), central memory (CD44+CD62L+) and effector memory (CD44+CD62L−) cells within the pool of CD8+ T cells in both tumor models." (PMID 36397148, 2022).
tumor (continued). "ZEB1, snail, CD44, and OCT4 have been reported in the literature to be involved in tumour de-differentiation, therefore it is plausible that this mechanism occurs in the tumour core, which is more often hypoxic and hosts stem cell niches." (PMID 36358805, 2022). "CD44 is also highly expressed in proliferating cells obtained from N + HNSCC metastasis, thereby highlighting its possible role in tumor progression." (PMID 36261806, 2022). "The inhibitory effect of PTS on the in-tumor mTOR pathway resulted in the downregulation of TGF-β, CD44, VEGF, and EGFR, which would have had the effect of retarding tumor-cell migration and invasion, thus reducing the potential risk of metastasis." (PMID 36077992, 2022). "In the tumor microenvironment (TME), the HA on the surface of the magnetic nanoparticles provided second-level guidance, as the highly expressed CD44 molecules (the receptor for HA) on the surface of tumor cells were interacted with HA." (PMID 35672752, 2022). "Cancer stem cells from either human GC cell lines or tumor tissues were isolated using cell surface markers such as CD24, CD44, CD54, CD71, CD90, CD133, Lgr5, ALDH1, EpCAM, and CXCR4." (PMID 36176765, 2022). "In this study, CBFB knockdown decreased tumor burden, bone metastasis, and markers of bone metastasis, including CXCR4, Snail, CD44, OPN, Runx2, and IL-6." (PMID 35903297, 2022). "HA is reflected as one of the main components of the ECM; similarly, it is the foremost ligand for CD44 and RHAMM, which are overexpressed in a range of tumor cell surfaces including colon cancer, human breast epithelial cells, lung cancer, and acute leukemia." (PMID 35860333, 2022). "Consistent with the strong anti-tumor phenotype, mice immunized with unmodified OVA-LNP or with m1Ψ modification of 100% showed significant expansion of effector CD8+ T cells (CD8+ CD44+ CD62L-)." (PMID 36311701, 2022). "Given that single CD44- and CD271 staining revealed the presence of variable amounts of positive cells in all tumor sections analyzed, we finally screened HNSCC sections for CD44+CD271+ tumor cells in an IF double-staining approach." (PMID 35215208, 2022). "For instance, Notch inhibition results in a reduction of CD44+/CD24−/low CSC population and tumor growth by sensitizing CSC to anticancer therapies." (PMID 36233074, 2022). "Other CSC markers stimulated by the Wnt/β‐catenin pathway include CD24, Prom1, CD44, and ALDH1, thereby enhancing tumor stemness." (PMID 36226253, 2022). "HA-SMA-CDF reaches the tumor site based on a strong permeability and retention EPR effect and reaches CD44 overexpressing pancreatic CSCs through an active targeting mechanism (CD44 receptor-mediated endocytosis)." (PMID 36182897, 2022). "CD44 has been introduced as a cancer stem cells marker in HCC together with CD90, CD133, CD24, and EpCAM, and is reported to be involved in tumor initiation and growth, cancer progression, and promoting metastasis." (PMID 35164326, 2022). "When LuCaP96 castrated and non-castrated samples were compared, 19/41 genes in CTCs and 5/41 genes in primary tumours were significantly different, with genes APLN and CD44 being significantly different in both comparisons." (PMID 35493092, 2022). "We show that the CD44- and CD36-expressing tumour cells only efficiently metastasize when using mitochondria as an energy source." (PMID 35768510, 2022). "In Patients 1 and 3, CD44 and CD49 were high in two samples and lower in the remaining three tissues, relative to those in the non-tumour tissue." (PMID 36362433, 2022). "While most of those studies showed that high CD44 expression is associated with advanced disease, metastasis, invasion and, lower OS, others have reported that a low CD44 expression correlates with more aggressive tumours or described a lack of correlation between survival and CD44 expression." (PMID 35055060, 2022).